CAP2 (cyclase associated actin cytoskeleton regulatory protein 2)
Description:
Involved in the regulation of actin polymerization.
Synonyms: CMD2I
Tractability: Antibody: UniProt places it where antibodies can reach, with medium confidence; its Gene Ontology location is reachable by antibodies, with medium confidence; the Human Protein Atlas places it where antibodies can reach. PROTAC: ubiquitination databases record sites on it; its protein half-life has been measured.
Gene: Protein-coding gene on chromosome 6 (17,393,375 to 17,557,792, forward strand). Ensembl gene ENSG00000112186.
Subcellular location: Cell membrane
Subcellular location (Human Protein Atlas): Cytosol; Nucleoplasm; Plasma membrane
Pathways (Reactome):
Developmental Biology: Role of ABL in ROBO-SLIT signaling
Gene Ontology:
Molecular function: identical protein binding; protein binding; adenylate cyclase binding; actin binding
Biological process: actin filament organization; activation of adenylate cyclase activity; cell morphogenesis; establishment or maintenance of cell polarity; signal transduction; cytoskeleton organization; presynaptic actin cytoskeleton organization
Cellular component: cytoplasm; plasma membrane; postsynaptic density
Genetic constraint (gnomAD): Loss-of-function variants: 19 observed, 36.53 expected, observed/expected ratio (o/e) 0.52, 90% interval 0.36 to 0.76. The upper end of that interval is the gene's LOEUF score, 0.76, which puts it in group 3 of 6, group 1 being the genes least tolerant of losing a copy. Missense variants: 349 observed, 422.68 expected, observed/expected ratio (o/e) 0.83, 90% interval 0.76 to 0.9. Synonymous variants: 146 observed, 155.04 expected, observed/expected ratio (o/e) 0.94, 90% interval 0.82 to 1.08.
Homologues: Orthologues: chimpanzee CAP2 (99% identical), macaque CAP2 (97% identical), guinea pig CAP2 (90% identical), dog CAP2 (90% identical), pig CAP2 (89% identical), mouse Cap2 (89% identical), rat Cap2 (87% identical), rabbit CAP2 (82% identical), tropical clawed frog cap2 (70% identical), zebrafish cap2 (61% identical), Drosophila melanogaster capt (48% identical), Caenorhabditis elegans cas-1 (41% identical), and 1 more. Paralogues in human: CAP1 (63% identical).
Diseases named in the same sentence as CAP2 in open-access papers:
CAP2 is named in the same sentence as 65 diseases in open-access papers, as found by Europe PMC text mining. Sharing a sentence is not in itself a finding about the gene and the disease. The quoted sentences say what the papers report.
dilated cardiomyopathy (10 papers, 2015 to 2025). Cardiomyopathy which is characterized by dilation and contractile dysfunction of the left and right ventricles. "Ablation of CAP2 in mice causes dilated cardiomyopathy associated with severe reduction in the heart rate." (PMID 40860890, 2025). "Ablation of CAP2 in mice causes dilated cardiomyopathy associated with severe reduction of the heart rate." (PMID 40463910, 2025). "In line with its enrichment in striated muscles, CAP2−/− mice displayed skeletal muscle and cardiac defects, and human genetic studies associated pathogenic CAP2 variants with nemaline myopathy or dilated cardiomyopathy." (PMID 39154297, 2024). "CAP2 deletion in mice leads to sudden cardiac death due to conduction abnormalities and dilated cardiomyopathy, and also causes delayed myofibril differentiation." (PMID 35628117, 2022). "Similarly, CAP2 mutations in humans lead to supraventricular tachycardia and severe dilated cardiomyopathy." (PMID 35628117, 2022). "Importantly, three of these genes were validated as ‘diagnostic’ genes given the strong evidence supporting causality derived from our data repository (CAP2-dilated cardiomyopathy, ITFG2-intellectual disability and USP53-liver cholestasis)." (PMID 33083013, 2020). "Ablation of CAP2 in mice results in dilated cardiomyopathy, accompanied by a significant reduction in heart rate." (PMID 40842442, 2025). "This holds true specifically for the ubiquitously expressed family member CAP113, while recent studies revealed arrhythmia, cardiac conduction defects as well as dilated cardiomyopathy in systemic and heart-specific CAP2 mutant mice." (PMID 33637797, 2021). "We reported previously that CAP2 knockout mice develop dilated cardiomyopathy, furthermore, it plays a role in skin repair during wound healing, and its ablation leads to changes in infiltration of inflammatory cells and contraction of wounds." (PMID 27507934, 2016). "CAP2 is expressed primarily in skeletal and heart muscle tissue, and a knockout of CAP2 in mice leads to defects in muscle architecture and function accompanied by severe dilated cardiomyopathy and muscle weakness." (PMID 37863260, 2023). "Taken together these data suggest that CAP2 mutant mice initially have normal cardiac function and conduction that degenerates later in life with ventricular conduction system disease and mild, dilated cardiomyopathy that is more pronounced in males versus females." (PMID 26616005, 2015). "The third gene relates to a severe early onset form of dilated cardiomyopathy (DCM) and congenital heart defects (CAP2 gene)." (PMID 33083013, 2020).
gastric cancer (7 papers, 2020 to 2024). A primary or metastatic malignant neoplasm involving the stomach. "In gastric cancer, cyclase-associated protein 2 (CAP2) bound to RACK1 and activated the SRC/FAK/ERK signaling pathway, leading to IL-4 and IL10 secretion, and M2 macrophage polarization." (PMID 38315284, 2024). "Moreover, CAP2 had been found to be upregulated in gastric cancer and was associated with lymph node and distant metastases, and considered as a molecular marker of gastric cancer." (PMID 32042970, 2020). "However, all the available researches have underlined an overexpression of CAP2 in hepatocellular carcinoma, malignant melanoma, breast cancer and gastric cancer." (PMID 32042970, 2020). "CD40, CAP2 proteins, and mRNAs expressions are closely related to prognosis, distant metastasis, and stage of patients with gastric cancer." (PMID 34386426, 2021). "This is in consistence with other studies that suggested CAP2 as a marker for malignant melanoma, breast cancer, and gastric cancer." (PMID 32042970, 2020). "CAP2 is upregulated in multiple tumors, such as breast cancer, gastric cancer, malignant melanoma, and it is also upregulated in early HCC and to a greater extent in advanced HCC." (PMID 32923383, 2020). "VWF, SHC1, and CAP2 have been reported to be elevated in LNM-positive patients with gastric cancer." (PMID 37158593, 2023). "Besides, CAP2 expression was mainly localized in the cytoplasm of gastric cancer cells and weakly expressed in noncancerous gastric tissues." (PMID 32042970, 2020).
cardiomyopathy (6 papers, 2015 to 2023). A disease of the heart muscle or myocardium proper. "It is worth noting that the combination of the heterozygous variants in CAP2, ADCY6, and SYNE2, associated with the loss of function in TPM2, could also be related to cardiomyopathy." (PMID 37744435, 2023). "A recent study showed that protein expression levels of CAP2 were up regulated in cardiomyopathy patients, but this gene might be responsible for T1D in patients with cardiomyopathy." (PMID 33827531, 2021). "Thus the sex-bias in CAP2 knockout mice may be a useful model system for studying sex-differences in the progression of cardiomyopathy and cardiac conduction disease." (PMID 26616005, 2015). "Ablation of CAP2 is lethal and mice lacking CAP2 develop cardiomyopathy and have a disarrayed sarcomeric organization." (PMID 27507934, 2016).
melanoma (5 papers, 2016 to 2022). A malignant, usually aggressive tumor composed of atypical, neoplastic melanocytes. "For example, it is known that CAP2 plays an important role in the invasion of malignant melanoma, and that its high expression is associated with a poor prognosis in patients with malignant melanoma." (PMID 35116193, 2022). "On the other hand, CAP2 has been found to be overexpressed in melanoma and hepatocellular carcinoma." (PMID 28423713, 2017). "CAP2 was upregulated in leukemia, gastric, breast, kidney, and liver cancer, whereas decreased in the bladder, brain, lung, prostate, oesophagus, and ovarian cancer, as well as sarcoma and melanoma." (PMID 28423713, 2017). "Their results suggest that CAP2 might be a useful prognostic marker in malignant melanoma." (PMID 32042970, 2020). "Melanoma cells revealed cytoplasmic CAP2 expression with no detectable staining among normal melanocytes." (PMID 32042970, 2020).
Alzheimer disease (4 papers, 2021 to 2023). A progressive, neurodegenerative disease characterized by loss of function and death of nerve cells in several areas of the brain leading to loss of cognitive function such as memory and language. "CAP2 has been identified as a crucial regulator of the physiological functions of these organs and alterations in CAP2 have been associated to many age‐related diseases, such as Alzheimer's disease (AD)." (PMID 37537790, 2023). "Moreover, CAP2 dysregulation has been implicated in synaptic defects of Alzheimer’s disease." (PMID 34204261, 2021). "Instead, CAP2 controls dendritic spine morphology and synaptic plasticity, and its dysregulation contributes to Alzheimer’s disease pathology." (PMID 34204261, 2021). "To assess whether DLG1 and CAP2 transcript alterations were selective for SCZ, we also measured their expression in the superior frontal gyrus of patients affected by neurodegenerative disorders, like Parkinson’s and Alzheimer’s disease." (PMID 35163460, 2022). "In addition, we investigated whether the mRNA and protein expression of CAP2, SAP97, and ADAM10 are also affected in patients with neurodegenerative disorders such as Parkinson’s Disease (PD) and Alzheimer’s Disease (AD), which are also characterized by spine defects." (PMID 35163460, 2022).
breast carcinoma (4 papers, 2016 to 2020). "The results showed that CAP2 was associated with poor survival in gastric and ovarian cancers, but with better survival in breast cancer." (PMID 28423713, 2017). "It has been also reported that CAP2 is overexpressed in breast cancer, and it was significantly associated with progesterone receptor expression and decreased overall survival, thereby might be considered as a biomarker for the prediction of breast cancer prognosis and survival." (PMID 32042970, 2020). "For example, in breast cancer, CAP2 expression was mainly localized in the cytoplasm of tumor cells, with some CAP2 subsiding in the nucleus." (PMID 32042970, 2020). "CAP2 was deregulated in various cancer types, but unregulated in liver, gastric, kidney, and breast cancer." (PMID 28423713, 2017). "High CAP2 expression showed a relatively good prognosis in breast cancer, whereas poor prognosis in gastric and ovarian cancers." (PMID 28423713, 2017). "We also examined expression of CAP2, the other CAP isoform, in these cells to confirm that CAP1 is indeed the predominate isoform in breast cancer cells." (PMID 27173014, 2016).
hepatocellular carcinoma (4 papers, 2011 to 2020). A malignant tumor that arises from hepatocytes. "Cyclase-associated protein 2 (CAP2) was listed as an up-regulated gene in early hepatocellular carcinoma (HCC)." (PMID 21989042, 2011). "CAP2 overexpression is observed in a stepwise manner during the hepatocellular carcinoma progression and, in the early stages, the invading tumor cells were CAP2-positive." (PMID 33072768, 2020). "Moreover, the overexpression of CAP2 correlates with portal vein invasion and intrahepatic metastasis, indicating CAP2 involvement in promoting the invasive behavior of hepatocellular carcinoma cells." (PMID 33072768, 2020). "Indeed, CAP2 overexpression is considered a poor prognostic biomarker for hepatocellular carcinoma patients." (PMID 33072768, 2020). "Interestingly, CAP2 and actin co-localized in the leading edge of lamellipodia from hepatocellular carcinoma cells." (PMID 33072768, 2020). "Furthermore, oligonucleotides array technology revealed CAP2 as one of the genes upregulated in early hepatocellular carcinoma." (PMID 33072768, 2020). "For instance, CAP2 has been found to be overexpressed in hepatocellular carcinoma." (PMID 28423713, 2017). "In addition, we explored the co-expression profiles for CAP2 with 20 genes across 225 liver carcinomas and 220 normal liver tissues, and 20 genes across 157 brain and 23 normal samples." (PMID 28423713, 2017). "In hepatocellular carcinoma, CAP2 expression was observed in the cytoplasm and the membranous or apical portion of progressed HCC in pseudoglandular patterns." (PMID 32042970, 2020).
schizophrenia (4 papers, 2017 to 2025). A major psychotic disorder characterized by abnormalities in the perception or expression of reality. "In addition, we confirmed Cap2, Chgb, Cpne6, Lynx1, and Mbp; which were selected among gene products implicated in schizophrenia and neurological disorders by the DAVID algorithm (p < 2.35E-03)." (PMID 28344592, 2017). "CAP2, a gene that regulates actin dynamics to shape spine density and dendritic complexity, is decreased in the hippocampus of individuals diagnosed with schizophrenia (SCZ)." (PMID 38263132, 2024).
liver cancer (3 papers, 2017 to 2024). An epithelial or non-epithelial malignant neoplasm that arises from the liver. "Through promoter binding, ATF2 and endoplasmic reticulum stress induce the expression of CAP2, promoting EMT in liver cancer cells." (PMID 39633985, 2024). "CAP2 was coexpressed with TP53BP2, ENA/VASP in the liver cancer, and CFL1, CFL2, DSTN, ACTB, ACTG1, and ROBO1." (PMID 28423713, 2017). "Given that CAP2 was already identified as a marker for early-stage liver cancer patients with negative alpha fetoprotein (AFP), we decided to focus our research analysis on the potential of ITGA6 as a diagnostic marker for early-stage liver cancer." (PMID 37627184, 2023). "CAP2 was coexpressed with TP53BP2 and ENA/VASP in liver cancer." (PMID 28423713, 2017).
prostate carcinoma (3 papers, 2015 to 2022). A carcinoma that arises from epithelial cells of the prostate gland. "For example, percentages of alterations in CAP2, CAP1, CFL1, CFL2, DSTN, ACTB, and ACTG1 genes among prostate cancer varied from 2.6–30% in individual genes (CAP2, 19%; CAP1, 13%; CFL1, 30%; CFL2, 21%; DSTN, 19%; ACTG1, 2.6%; ACTB, 21%;); the CFL1 gene was amplified predominantly in prostate cancer." (PMID 28423713, 2017). "The percentages of alterations in these genes among prostate cancer varied from 13-30% for individual genes (CAP2, 19%; CAP1, 13%; CFL1, 30%; CFL2, 21%; DSTN, 19%); the CFL1 gene was amplified predominantly in the prostate cancer type." (PMID 28423713, 2017). "The cBioPortal and Tumorscape analysis found that frequency of 40.2–20% with the rank order mainly in prostate cancer with CAP1, CAP2 alteration ranged from 38.3–19.8%." (PMID 28423713, 2017). "The cBioPortal analysis found that the frequency of 40.2–20% with the rank order mainly in prostate cancer with CAP1 and CAP2 alteration ranged from 38.3–19.8%." (PMID 28423713, 2017).
glioma (2 papers, 2016 to 2020). A benign or malignant brain and spinal cord tumor that arises from glial cells (astrocytes, oligodendrocytes, ependymal cells). "Kaplan-Meier analysis revealed that high CAP2 expression was associated with poor prognosis of patients with glioma (P < 0.05)." (PMID 32042970, 2020). "The present study demonstrated that high CAP2 expression level was associated with poor overall survival in patients with gliomas." (PMID 32042970, 2020). "Further studied are indeed required to enrich the molecular mechanisms underlying roles of CAP2 in gliomas." (PMID 32042970, 2020). "Furthermore, high CAP2 expression in gliomas was significantly associated with higher grades tumors (grade III and IV) compared to low-grade tumors (grade I and II)." (PMID 32042970, 2020). "High expression of CAP2 was also associated with advanced tumor grades among gliomas." (PMID 32042970, 2020). "In accordance, we believe that more data and follow up is required to assess the correlation of CAP2 expression with clinical outcomes and to compare CAP2 expression among the different types of glioma tumors as well." (PMID 32042970, 2020). "Glioma samples were categorized into two groups according to the expression of CAP2 as having low (IRS ≤3) and high (IRS ≥4) CAP2 expression." (PMID 32042970, 2020). "In conclusion, we demonstrated, that CAP2 was noticeably overexpressed in gliomas compared with normal tissues." (PMID 32042970, 2020). "The association between CAP2 expression level and clinicopathological characteristics was determined, and the prognostic significance of CAP2 in gliomas was evaluated by survival analysis." (PMID 32042970, 2020). "Although our study is retrospective in nature and the sample size is small, the obtained results propose CAP2 as a promising molecular biomarker for gliomas." (PMID 32042970, 2020). "CAP2 is overexpressed in glioma and it is proposed as a potential prognostic biomarker for patients with gliomas." (PMID 32042970, 2020). "In our study, we first sought to assess the expression patterns of CAP2 gene in human glioma tumor tissues." (PMID 32042970, 2020). "Earlier studies confirmed that CAP1, a homolog of CAP2, is overexpressed in many cancers, and its expression was correlated with tumor grades in human epithelial ovarian cancer and glioma, and with the degree of malignancy in glioma." (PMID 32042970, 2020). "A significant difference in CAP2 expression was noted between the normal brain tissues and glioma (P < 0.001, χ2) with more pronounced expression in tumor specimens." (PMID 32042970, 2020). "Our results revealed high expression of CAP2 protein in tumors of gliomas compared to normal tissues and normal areas adjacent to tumors." (PMID 32042970, 2020). "For a better understanding of the potential role of CAP2 in gliomas, we investigated and compared the differential expression of CAP2 in glioma and normal brain tissues." (PMID 32042970, 2020). "We further analyzed the relationship between CAP2 expression and the clinicopathological characteristics of patients with gliomas." (PMID 32042970, 2020). "Our current data showed that CAP2 is significantly overexpressed at protein levels in gliomas compared to normal brain tissues and normal areas adjacent to tumors using IHC assay." (PMID 32042970, 2020). "CAP2 expression at the protein level was analyzed in 47 human paraffin-embedded gliomas and normal brain tissues by automated immunohistochemical analysis." (PMID 32042970, 2020). "High CAP2 expression is suggestive of the involvement of this protein in multistep carcinogenesis of gliomas." (PMID 32042970, 2020). "First, although this is the first translational research paper to evaluate the expression patterns of CAP2 in human glioma tumor tissues, the sample size is relatively small and hence, the results obtained require conducting subsequent studies on a larger cohort." (PMID 32042970, 2020).